CCR2 (C-C motif chemokine receptor 2)
Diseases named in the same sentence as CCR2 in open-access papers (continued):
Sharing a sentence is not in itself a finding about the gene and the disease.
colorectal cancer (27 papers, 2016 to 2025). A primary or metastatic malignant neoplasm that affects the colon or rectum. "Second, high CCR2 expression in patient samples was associated with shorter relapse-free survival (RFS) of colorectal cancer patients (981 ± 865 days) compared with low expression (1403 ± 1279 days)." (PMID 30764543, 2019). "Finally, higher expression of CCL7 receptor CCR2 (C-C chemokine receptor type 2) was associated with shorter overall survival of colorectal cancer patients." (PMID 30764543, 2019). "Moreover, high CCR2 expression was also associated with shorter overall survival (OS) of colorectal cancer patients (1219 ± 988 days) compared with low expression (1622 ± 1197 days)." (PMID 30764543, 2019). "In colorectal cancer (CRC), CAFs sorted from CCR2-deficient tumors showed aberrant collagen production such as reduced collagen I and XIV and increased collagen VI, identifying an interaction between TAMs/TIMs and CAFs." (PMID 38716730, 2024). "Targeting the MDSC-related CCL2(MCP1)–CCR2 pathway holds promise as a therapeutic approach, particularly in refractory colorectal cancer." (PMID 39456702, 2024). "The study was designed to assay the efficacy of cenicriviroc (CVC) on the progression of mouse colorectal cancer by downregulation of CCR2_CCL2." (PMID 37325423, 2023). "The results indicated that DHZCP inhibits colorectal cancer liver metastasis, likely associated with blocking CCL2/CCR2 activation in the liver and suppressing the CCL2-mediated M2-skewing paradigm." (PMID 36105201, 2022). "Even though our study does not provide a strong link between the in situ expression pattern of CCL7 and CCR2, it sets the stage for future studies analyzing CCL7/CCR2 axis in colorectal cancer progression." (PMID 30764543, 2019). "This is reminiscent of findings in colorectal cancer, where collagen deposition can be mediated in part through CCR2+ macrophages, and depletion of these macrophages inhibits tumor growth." (PMID 30990165, 2019). "Our tissue microarray (TMA) analysis revealed that CCR2 is a predictive factor for the overall survival (OS) of colorectal cancer patients." (PMID 30764543, 2019). "Altogether, our study identified CCL7 as a factor affecting lung metastasis in CT26 colon cancer model and its receptor, CCR2, as a predictor of the overall survival of colorectal cancer patients." (PMID 30764543, 2019). "In the following sections, we highlight effects of CCL2/CCR2 signaling in several experimental studies on metastatic cancers, with a particular focus on prostate, breast and colorectal cancers." (PMID 26885690, 2016). "Altogether, we showed that CCL7 is essentially involved in the progression of colorectal cancer in a CT26 mouse model and that the expression of its receptor CCR2 could be related to a different outcome pattern of patients with colorectal carcinoma." (PMID 30764543, 2019). "Likewise, binding or either CCL8 or CCL2 to CCR2 on colorectal cancer cells can provoke a similar increase in migration and invasion." (PMID 26885690, 2016). "Hence, theoretically, targeting the CCL2(MCP1)/CCR2/MDSC pathway could potentially serve as an immune target for refractory colorectal cancer (CRC)." (PMID 39456702, 2024). "A previous study showed that NT5DC2 deletion obviously reduced the tumor-associated macrophage (TAM) recruitments through suppressing CCL2/CCR2 and AKT/NF-κB signaling pathways in colorectal cancer." (PMID 35047040, 2022). "Exosomes from colorectal cancer cell lines affected CCL7 secretion from CAFs, possibly via the miRNA let-7d, and interfered with the migration of CCR2+ monocytic THP-1 cells in vitro." (PMID 33175885, 2020). "In a series of studies utilizing mouse models of colorectal cancer, the employment of CCR2 antagonists (e.g., RS504393, RS102895) or the suppression of the CCL2/CCR2 axis has been demonstrated to result in a substantial reduction in the infiltration of TAMs within tumors." (PMID 40109347, 2025).
colorectal cancer (continued). "One of the reasons for this discrepancy might be that Scott et al20 originally described CCR2+CD103−SIRPα+ DC in murine cells and confirmed their presence in human samples using tissue resections from patients with colorectal cancer." (PMID 26866054, 2016).
diabetic nephropathy (27 papers, 2015 to 2026). "Genetic ablation of macrophage migration associated molecules such as CCR2 or its ligand MCP1 attenuated diabetic kidney disease." (PMID 31191312, 2019). "The inhibition of MCP-1/CCR-2 decreased macrophages infiltration and successfully alleviated the progression of diabetic nephropathy." (PMID 37440431, 2023). "According to research, macrophages play a direct role in the renal injury of diabetic nephropathy, and genetic CCR2 deletion provides kidney protection in renal injury." (PMID 37760894, 2023). "For instance, studies have investigated the prevention of diabetic nephropathy progression through the blocking of monocyte recruitment with small molecules, such as a specific CCR2 or dual CCR2/CCR5 antagonist." (PMID 37954596, 2023). "Several reports have shown that the activation of macrophage induction through the CCL2/CCR2 axis particularly induces injury to the nephron and renal tubes in CKDs, such as glomerulonephritis and diabetic kidney diseases." (PMID 33159802, 2021). "Although there is accumulating evidence of the clinical utility of the inhibition of CCR2 by PG, its benefits in human diabetic nephropathy remain to be investigated." (PMID 32704573, 2020). "However, pharmacological inhibition of CCR2 has shown renal protection in experimental and clinical diabetic kidney disease." (PMID 35090403, 2022). "Targeting MCP-1/CCL2/CCR2 was also protective in experimental diabetic nephropathy." (PMID 34307414, 2021). "However, clinical study of a dual chemokine CCR2/5 receptor antagonist related to the albuminuria in adults with diabetic nephropathy was discontinued despite the safety profile was shown." (PMID 33968046, 2021). "The use of PG as a therapeutic modality for diabetic nephropathy as well as type 2 diabetes requires further investigation, which may elucidate the potential role of CCR2." (PMID 32704573, 2020). "Although we evaluated urinary MCP‐1 concentration as a candidate biomarker of the severity of diabetic nephropathy, monitoring of pharmacological inhibition of CCR2 may be required to further investigate the efficacy of PG in future definitive trials." (PMID 32704573, 2020). "Furthermore, inhibition of MCP‐1 and CCR2 has been shown to ameliorate renal function and pathological development in experimental models of diabetic nephropathy." (PMID 32704573, 2020). "Our previous study has also demonstrated that CCL2/CCR2 signaling axis might be a potential therapeutic target in diabetic kidney disease through improving podocyte permeability, actin cytoskeleton, and podocyte motility." (PMID 31498850, 2019). "Several studies have reported that the development of diabetic nephropathy could be blocked in type 2 diabetic mice by using CCR2 inhibitors such as RS504393 and RO523444." (PMID 31498850, 2019). "An upregulation of CCR2 occurs before macrophage infiltration in human diabetic nephropathy." (PMID 31498850, 2019). "Thus, not surprisingly, urinary MCP-1 has been suggested as a diagnostic marker for progressive renal injury in diabetic nephropathy, and pharmacological targeting of MCP-1 and its receptor CCR2 has been proposed as a novel approach to treat diabetic kidney disease." (PMID 29772789, 2018). "Several reports have described the involvement of the CCL2/CCR2 axis in the final common pathway in animal models of diabetic kidney disease, and inhibitors of the CCL2/CCR2 axis were effective in ameliorating CKD conditions in these models." (PMID 33159802, 2021). "A number of CCL2/CCR2 axis inhibitors, such as CCX140-B and emapticap pegol, have also been developed, and have demonstrated a degree of clinical benefit for diabetic kidney disease in humans." (PMID 33159802, 2021). "Recently, phase 2 studies of certain inhibitors of the CCL2/CCR2 axis, such as CCX140-B and emapticap pegol, have been conducted in diabetic kidney disease patients." (PMID 33159802, 2021).
diabetic nephropathy (continued). "In the CCR2 knockout and STZ-induced diabetic nephropathy-prone (DBA/2J) mouse model, kidney protection effects are observed after nine weeks of diabetes." (PMID 32365893, 2020).
Hepatic steatosis (27 papers, 2012 to 2025). Steatosis is a term used to denote lipid accumulation within hepatocytes. "Associations between the Ccr2-positive Kupffer cells (hepatic residential macrophage) and choline-deficient amino acid-defined diet-induced hepatic steatosis and fibrosis have been identified." (PMID 35634491, 2022). "Genetic deficiency of chemokine receptor 2 (CCR2) and pharmacological antagonism of CCR2 in mice lowered macrophage content and the inflammatory profile of adipose tissue and ameliorated hepatic steatosis." (PMID 33530440, 2021). "Assessment of the NAFLD activity score (NAS) components revealed beneficial effects of FGF21 administration on hepatic steatosis, which was confirmed by a lower hepatic triglyceride content, while CCR2/5 inhibitor treatment was associated with reduced lobular inflammation." (PMID 35743140, 2022). "Indeed, CCR2 deficiency reduced liver steatosis in DIO mice by suppressing the recruitment of CCR2 + Ly6Chigh monocytes." (PMID 34360773, 2021). "Indeed, pharmacological antagonist of CCR2 reduced liver steatosis in obese and diabetic mice (db/db), and CCL2 deficiency reduced the accumulation of hepatic triglycerides in HFD and db/db mice." (PMID 28115795, 2017). "Thus, interruption of the CCL2/CCR2 pathway may provide an effective therapeutic strategy for attenuating the progression of liver steatosis and of associated metabolic disorders." (PMID 24646914, 2014). "Previously, our group has observed that RS102895, a CCR2 inhibitor, can restore diabetic-induced renal nephropathy and hepatic steatosis in db/db mice." (PMID 31498850, 2019). "MCP-1 expression in hepatocytes is increased in animals fed a high-fat diet and leads to the hepatic recruitment of CCR2+ myeloid cells that promote hepatic steatosis." (PMID 28420094, 2017). "In this study, we demonstrated that CCR2 inhibitor alleviates hepatic steatosis and elucidated how CCR2 inhibitor reduces hepatic steatosis." (PMID 25816097, 2015). "The expression of MCP-1 in hepatocytes is increased in animals fed a HFD and leads to the hepatic recruitment of CCR2+ myeloid cells that promote hepatic steatosis." (PMID 26197341, 2015). "In this study, we investigated the protective effect of CCR2 inhibitor on hepatic steatosis in a diabetic mouse model." (PMID 25816097, 2015). "Myeloid/macrophage-specific KO models such as IKK-β or CCR2 that impair inflammatory responses in Kupffer cells show attenuation of hepatic insulin resistance in the setting of high-fat feeding, despite the full development of hepatic steatosis." (PMID 36177037, 2022). "This study is the first to describe the mechanism of CCR2 inhibitor in hepatic steatosis, and supports the involvement cross talk between MCP-1 and CCR2, which could activate inflammatory responses and blunt insulin signaling in the fatty liver." (PMID 25816097, 2015). "We examined whether CCR2 inhibitor improves ER stress-induced hepatic steatosis in type 2 diabetic mice." (PMID 25816097, 2015). "Therefore, CCR2 inhibitor may be a useful therapeutic agent in ameliorating fatty liver in type 2 diabetes." (PMID 25816097, 2015). "Similarly, treatment with the CCR2 inhibitor propagermanium could improve diet-induced metabolic disorders such as insulin resistance and liver steatosis." (PMID 24646914, 2014). "Pharmacological inhibition of CCR2 and genetic deletion of CCL2 reduced liver steatosis in obese mice." (PMID 31921154, 2019). "No other studies so far have described a detailed mechanism involving CCR2 inhibitor and NAFLD, except for its inhibition of adipose tissue-induced hepatic steatosis." (PMID 25816097, 2015). "Our study support and extend recent findings demonstrating the role of CCR2 and CD44 in inflammation during hepatic steatosis." (PMID 23762326, 2013). "CCR2-dependent recruitment of myeloid cells to the liver and CCL2-dependent development of hepatic steatosis were also demonstrated by other studies." (PMID 23964268, 2013).
Hepatic steatosis (continued). "Our data reveal the independent and overlapping roles of CCR2 and CD44 in development and progression of hepatic inflammation during fatty liver disease." (PMID 23762326, 2013). "Obese mice lacking the MCP1 receptor CCR2 have increased adiponectin expression, ameliorated hepatic steatosis, and improved systemic glucose homeostasis." (PMID 35980018, 2022). "CCL2/CCR2 has been identified as chemokines that promote monocyte infiltration into the injured liver; therefore, CCL2/CCR2 is likely to be applied in clinics in the treatment of fatty liver disease in the future." (PMID 34956171, 2021). "Interestingly, treatment with the CCR2 antagonist RS504393 was able to ameliorate hyperglycaemia, liver steatosis and liver inflammation." (PMID 24646914, 2014). "Interestingly, it seems that there was no synergistic effect in hepatic steatosis when cells were co-treated with CCR2 inhibitor and rapamycin." (PMID 25816097, 2015). "CCR2 plays important roles in adverse effects of PM2.5 by modulating VAT inflammation and hepatic steatosis but not glucose utilization in skeletal muscle." (PMID 24149114, 2014).
ischemic stroke (27 papers, 2012 to 2026). A stroke disorder caused by obstruction of blood flow to the brain, due to thrombotic (local blood clot formation) or embolic (due to a blood clot or other material traveling from another site) event. "In this study, we attempted to investigate the interaction between estradiol levels and inflammatory genes including MCP-1, CCR2, and E-selectin on the risk of ischemic stroke." (PMID 28351426, 2017). "The authors demonstrated that RLC-mediated protection against ischemic stroke injury is disrupted by the adoptive transfer of CCR2-deficient monocytes, highlighting the importance of the RLC-induced shift of monocytes into the CCR2+ monocyte subset in attenuating ischemic stroke outcomes." (PMID 33193029, 2020). "Studies have found that CCR2-dependent monocytes/macrophages exacerbate acute brain injury after ischemic stroke in mice but are beneficial for long-term functional recovery." (PMID 41601622, 2026). "In a previous study on ischemic stroke in rats, CCR2 overexpressed BMSCs enhanced migration to the ischemic hemisphere and improves the therapeutic outcomes." (PMID 40472038, 2025). "The CCL2/CCR2 axis mediates monocyte migration in ischemic stroke and affects the integrity of the BBB." (PMID 37452512, 2023). "The population of CCR2+ classical monocytes was comparable in controls [97.7% (94.2–98.2)] and ischemic stroke patients [96.3% (95.2–97.7), U = 0.24, p = 0.24]." (PMID 33918875, 2021). "CCR2 is expressed on a subset of neutrophils and is regulated by immune activation enabling the neutrophils to invade the brain after ischemic stroke." (PMID 33918875, 2021). "When comparing CCR2+ neutrophil cell populations, we found a trend towards more CCR2+ neutrophil populations in ischemic stroke patients [1.68% (1.09–4.44)] compared with controls [0.93% (0.78–2.04), U = 52.5, p = 0.07]." (PMID 33918875, 2021). "In the present study, we also found CCL2 and CCR2 levels to be significantly increased in the blood of our ischemic stroke patients." (PMID 33918875, 2021). "C-C Motif Chemokine Receptor 2 (CCR2) is positively regulated in the first 24 h after ischemic stroke." (PMID 32974331, 2020). "Third, only SNPs of MCP-1, CCR2, and E-selectin genes were selected to investigate the relationship with ischemic stroke." (PMID 28351426, 2017). "In our study, CCR2 rs1799864 and CCR5 rs1799987 were associated with ischemic stroke only in the hypertensive group." (PMID 22769019, 2012). "CCR2 is the main receptor that binds to CCL2 in ischemic stroke." (PMID 37452512, 2023). "The mechanism of the CCL2/CCR2 axis in ischemic stroke can be explained as follows." (PMID 37452512, 2023). "Nonetheless, the correlation of CCR2 with time is consistent with active recruitment of monocytes from the bone marrow, which is in line with experimental data where monocytes begin to accumulate around day 3 or later after ischemic stroke." (PMID 36803375, 2023). "Therapeutic approaches regulating CCL2/CCR2 expression may alleviate the symptoms and pathologies of ischemic stroke." (PMID 35794095, 2022). "CCR2+ non-classical monocyte cell populations were also comparable in controls [0.60% (0.42–1.31)] and ischemic stroke patients [0.78% (0.52–1.19), U = 75, p = 0.46], as were CCR2+ intermediate monocyte cell populations [Ctl: 51.2% (43.8–57.6) and IS: 54.2% (49.0–62.4), U = 65, p = 0.24]." (PMID 33918875, 2021). "Others have found that neutrophils can upregulate CCR2 expression in response to inflammatory mediators, and it remains to be investigated if this activation of neutrophils also takes place following ischemic stroke." (PMID 33918875, 2021). "In our study, the neutrophils showed a trend towards increased CCR2 expression in ischemic stroke." (PMID 33918875, 2021). "Therefore, it has been reported that therapeutic intervention through CCR2 at the level of inflammatory cell recruitment after ischemic stroke is beneficial." (PMID 31572378, 2019).
ischemic stroke (continued). "Hence, CCR-2-dependent monocyte/macrophages not only aggravate brain injury but also alleviate functional recovery after ischemic stroke." (PMID 31291966, 2019). "There were no prominent associations between SNPs on MCP-1, CCR2, or E-selectin genes in addition to rs2076059, which was located on E-selectin and significantly increased the risk of ischemic stroke under the dominant model." (PMID 28351426, 2017). "There were no nominal associations of CCR2 rs1799864 or rs1799865 with the risk of ischemic stroke in our study." (PMID 28351426, 2017). "For example, therapeutic strategies that aim at specifically boosting CCR2+ pro-inflammatory monocytes (Ly6Chigh) in the acute phase of ischemic stroke might limit brain injury progression and exacerbation." (PMID 26941641, 2016). "Thus, genetic deletion or manipulation of CCL2/CCR2 expression may be a therapeutic target for ischemic stroke." (PMID 31291966, 2019). "As CCR2+ monocytes mediate platelet‐derived growth factor (PDGF) beta and PDGF receptor beta messenger RNA (mRNA) expression in ischemic stroke, it can be inferred that monocytes support pericyte differentiation." (PMID 37452512, 2023). "In a model of ischemic stroke, CD36 KO mice had reduced CCL2/CCR2 expression." (PMID 37452512, 2023). "We found comparable CCR2 expression patterns on monocytes and neutrophils in healthy controls and ischemic stroke patients, suggesting that CCR2 expression on peripheral monocytes and neutrophils is not regulated in response to ischemia." (PMID 33918875, 2021). "In contrast to the few studies that investigated the implication of CCR2+ pro-inflammatory (Ly6Chigh), the role of anti-inflammatory monocytes (Ly6Clow) in ischemic stroke has never been investigated or addressed." (PMID 26941641, 2016). "Blood-derived monocytes (Ccr2+CD68–), inflammatory macrophages (Ccr2+CD68+) and activated perivascular macrophages (CD206+CD68+) in the perivascular space are present in the cortical ischemic stroke area within the first days after PT, coinciding with massive fibrinogen deposition." (PMID 41280671, 2025). "We propose that infiltrated pro-inflammatory CCR2+MHC-II+ macrophages may exert some pro-neurogenic functions such as clearance of cell debris after brain injury, which could be efficient at neurogenesis and regeneration process after ischemic stroke." (PMID 29866203, 2018).